CD47 (CD47 molecule)
Diseases named in the same sentence as CD47 in open-access papers (continued):
Sharing a sentence is not in itself a finding about the gene and the disease.
cancer (continued). "It is currently poorly understood about the mechanisms involved in the regulation of CD47 protein degradation in cancer." (PMID 36823443, 2023). "CD47 immune checkpoint inhibitors have emerged as promising immunotherapy in cancer treatment thanks to their ability to facilitate the concomitant inhibition of the “do-not-eat-me” signal and to boost antitumor T-cell response." (PMID 37153563, 2023). "CD47 is often overexpressed on cancer cells, acting as a “don’t eat me” signal that allows cancer cells to evade detection by the immune system." (PMID 38188674, 2023). "CD47 is consequently overexpressed on various types of tumors, allowing cancer cells to escape macrophage phagocytosis and immune surveillance." (PMID 36882648, 2023). "Addressing these challenges will be critical in advancing CD47-targeted therapy toward becoming a more effective treatment option for cancer patients." (PMID 38188674, 2023). "Currently, results of phase I and II studies investigating the efficacy of anti-CD47 in different types of cancer show promising results, particularly in combination with reference treatments where they lead to a decrease in toxicity." (PMID 37143666, 2023). "The interaction between CD47 and its receptor SIRPα on macrophages inhibits the phagocytosis of cancer cells." (PMID 38188674, 2023). "As such, CD47 has been gradually used in cancer treatment, leading to the development of relevant blocking drugs targeting CD47." (PMID 37484024, 2023). "Cancer cells express CD47 highly, which binds to SIRPα on phagocytes, leading to the evasion from immune surveillance." (PMID 36882399, 2023). "A major breakthrough in cancer immunosurveillance was the identification of ‘don’t eat me’ signals such as CD47, which can be upregulated on cancer cells to inhibit macrophage phagocytosis." (PMID 37709767, 2023). "In particular, the ability of the GPR84 agonist 6-OAU to promote phagocytosis of cancer cells induced by CD47 blockage and the specific expression of GPR84 in TAMs12 implied a potential role of GPR84 in cancer immune surveillance." (PMID 37709767, 2023). "We suggest that this increased macrophage infiltration additionally contributes to THC formation in low CD47-expressing cancer cells." (PMID 37848444, 2023). "Given its roles immune evasion and TME regulation, CD47 has emerged as a promising therapeutic target for cancer treatment." (PMID 38188674, 2023). "CD47 (cluster of differentiation 47), a glycoprotein ubiquitously expressed on the surface of various cancer cells, interacts with the SIRPα protein expressed on macrophages." (PMID 36823443, 2023). "(F) Favorable %survival with a high level of calreticulin and a low level of CD47 in all cancer patients." (PMID 36943734, 2023). "The expression of STC1, AKR1B1, RPL5, and CD47 was increased, while HLA-A was downregulated along cancer invasion by immunohistochemical staining in clinical samples." (PMID 36816947, 2023). "Expanding the use of CD47-targeted therapy beyond hematological malignancies to other cancer types is also a future direction for research." (PMID 38188674, 2023). "We then investigated the effect of CD47 knockdown on tumorigenesis in mice in vivo and on the phagocytosis of cancer cells by KCs in vitro." (PMID 36860925, 2023). "Increasing evidence demonstrates that blocking CD47 interaction with SIRPα can enhance cancer cell clearance by macrophages." (PMID 36726125, 2023). "Additional mechanistic studies to investigate CD47–integrin interactions in different cancer models are needed to better understand the generalizability of their cellular effects." (PMID 37958404, 2023). "In various cancers, CD47 acts as a self-signal to inhibit phagocytosis using interacting with the macrophage receptor SIRPα 11,18." (PMID 36860925, 2023). "CAR T-cell therapy can target CD47 by genetically modifying a patient’s T cells to recognize and attack cancer cells." (PMID 38188674, 2023).
cancer (continued). "CD47 blockade not only enhances the macrophage phagocytosis of cancer cells but also directly impacts stromal cell function and the TME." (PMID 38188674, 2023). "MCA911 was used as the primary antibody to detect the expression of CD47 on different cancer cell lines." (PMID 36939440, 2023). "CD47 has a complex and multifactorial role in anti‐cancer immunity and is involved in the regulation of different immune cell activities." (PMID 36598153, 2023). "Recent studies have revealed that CD47 is a highly expressed anti-phagocytic signal in several types of cancer, and therefore, blocking of CD47 has shown an effective therapeutic potential in cancer immunotherapy." (PMID 38125492, 2023). "CD47 functions in immune homeostasis related to cancer prognosis, and its expression is closely related to immune infiltration." (PMID 36882399, 2023). "Simultaneously, RRX-001 reduces CD47 protein levels, aiding in preventing immune escape by calreticulin-rich cancer cells." (PMID 37951973, 2023). "CD47-mediated signaling is complex, highlighting its potential as a therapeutic target for cancer treatment." (PMID 38188674, 2023). "For example, CD47 on the platelet surface can interact with immune cells to inhibit immune clearance, and cancer cells can be homotypically targeted." (PMID 37507707, 2023). "In B16F10 and MC38 murine cancer cells, inserting CD47 or/and IFN-γ into MyxV_0100 only slightly interfered with infection and replication as compared to the control virus." (PMID 37835397, 2023). "Several human cancers have been shown to evade the immune system by upregulating CD47 on the cell surface and exploiting this mechanism that functionally prevents the unnecessary destruction of normal “self” cells." (PMID 37373873, 2023). "The Western blot result showed that bioinspired liposomes retained the characteristic proteins on the platelet membrane, including the platelet-specific CD41, immunomodulatory CD47 and cancer-targeted P-selectin." (PMID 36839952, 2023). "Inhibitors of phagocytosis are transmembrane proteins, also defined “don’t eat me” onco-proteins, expressed in cancer cells, and CD47 is a “don’t eat me” phagocytosis checkpoint, well expressed in a multitude of cancer types." (PMID 36854896, 2023). "CD47 blockade not only enhances macrophage-mediated phagocytosis of cancer cells but also directly affects stromal cell function and the TME." (PMID 38188674, 2023). "CD47 protein, expressed in both healthy and cancer cells, plays a crucial role in blocking the cytotoxic activity of myeloid cells by delivering a “do not eat me signal” upon binding to the signal-regulatory protein alpha (SIRPα) receptor on macrophage cells." (PMID 37368179, 2023). "CD47-targeted therapies show promise in both preclinical and clinical studies, with the potential to improve outcomes for cancer patients." (PMID 38188674, 2023). "The impressive success and advancements in CD47 cancer immunotherapy have generated hope and opened new avenues for innovative approaches in treating a wide range of noncancerous ailments." (PMID 38125492, 2023). "CD47 is an overexpressed protein on many cancer cells that plays a critical role in regulating immune cell interactions within the TME." (PMID 38188674, 2023). "RRx-001, a multi-functional drug used in clinical trials such as NCT02518958, not only can promote M1-TAM phenotype but also can be used as an inhibitor of CD47 on cancer cells and SIRPα on macrophages." (PMID 38035101, 2023). "Altogether, these results provide evidence for a shift in macrophage populations during the stepwise progression from normal tissue to cancer, accompanied by the upregulation of the CD47/SIRPα axis." (PMID 36442992, 2023). "It would also be helpful for a deeper understanding CD47-relevant cellular immune response and cancer development and for developing new strategies of immunotherapy targeting this adhesion molecule interaction." (PMID 37241964, 2023).
cancer (continued). "Increasing evidence has demonstrated that blocking the CD47 interaction with SIRPα can enhance cancer cell clearance by macrophages." (PMID 38068428, 2023). "Current evidence indicates that CD47 is widely expressed in various normal human cell types, as well as in the membrane of different cancer cell types." (PMID 36726125, 2023). "The TCGA dataset and our TMA results showed that LIMP-2 was generally positively correlated with immune checkpoints (e.g., PD-L1, CD47, and B7-H3) in a variety of cancers, including HNSCC." (PMID 37291150, 2023). "Promising results have been observed in preclinical studies and early-phase clinical trials, positioning CD47-targeted therapy as a potential breakthrough in cancer immunotherapy." (PMID 38188674, 2023). "Numerous studies have indicated that CD47 is critical for treatment, prognosis, and diagnosis of a variety of malignancies, in which the most notable function of the CD47/SIRPα axis regards cancer therapy." (PMID 36726125, 2023). "Treatment with anti-CD47 or anti-SIRPa antibodies increased phagocytosis of cancer cells by TAMs and resulted in increased priming of CD8+ T to exhibit cytotoxic functions." (PMID 37359522, 2023). "Their simulation results showed that oxidation of CD47 reduced its binding affinity to SIRPα on innate immune cells, thereby decreasing the chance of cancer cells evading immune cells." (PMID 37759771, 2023). "Sensitivity/specificity results for ICG-anti-CD47 targeting of cancerous lesions in the human bladder specimens: carcinoma vs. normal." (PMID 36937442, 2023). "We validated the stepwise increase in the expression of these proteins from normal colorectal tissue to carcinoma (CD47, Spearman Rho=0.47, p=6.5×10−6; SIRPα, Spearman Rho=0.60, p=2.2×10−9)." (PMID 36442992, 2023). "Cell surface CD47 is a ligand for signal regulatory protein-α (SIRPα), a protein expressed on macrophages and dendritic cells, allowing cancer cells to send inhibitory signals to macrophages and impede phagocytosis and immune response." (PMID 35372077, 2022). "Our data therefore support the notion that SIRPγhi cancer cells, which are CSLCs, can maintain CD47 expression in bulk cancer cells through autocrine/paracrine signaling." (PMID 35229723, 2022). "Based on previous studies, we know that CD47 is abundantly expressed in many tumors, and it plays an important role in macrophages, affecting the development of cancer." (PMID 35678681, 2022). "In this review, we discuss the role of neutrophils in cancer and describe the contribution of CD47-SIRPα as an innate immune checkpoint for neutrophils." (PMID 35884427, 2022). "The results showed that the unfolded proteins HSPA5, HYOU1, and PDIA4 were associated with survivability in cancer, and HSPA5 was positively and significantly correlated with CD47, and induced by CD47 in OSCC cells lines." (PMID 35678681, 2022). "CD47-SIRPα inhibition shows promise in cancer therapy; selective SIRPα blockade in combination with cytotoxic therapies in particular seem to maximize anti-tumoral benefit." (PMID 36439116, 2022). "Further molecular study is needed to identify the cancer-specific immune evasion mechanism of CD47 in ccRCC." (PMID 36291980, 2022). "CD47 is commonly overexpressed on the cell surface of many cancers, providing a “Don't eat me” signal that engages SIRPα on macrophages and prevents phagocytosis." (PMID 36369063, 2022). "CD47 on the cell surface is overexpressed in various cancer cells to help avoid the killing by innate immune cells." (PMID 35697717, 2022). "A study about CD47-based cancer immunotherapy revealed that accumulative Bifidobacterium in TME facilitates local anti-CD47 treatment by a stimulator of interferon genes (STING)- and interferon-dependent fashion." (PMID 36523986, 2022). "Here, we review the role of neutrophils in antibody therapy in cancer and their regulation by the CD47-SIRPα innate immune checkpoint." (PMID 35884427, 2022).
cancer (continued). "In other words, CD24 can be modified like CD47, or as a complement to CD47, blocked in cancer cells expressing CD47 and CD24 simultaneously." (PMID 36297672, 2022). "Primarily, increased cancer cell phagocytosis resulting from disruption of the CD47/SIRPα cross talk leads to enhanced presentation of antigens and CD8+ T cell proliferation in vitro." (PMID 35978372, 2022). "One of these stimulatory substances is known to act as an agonist peptide to activate CD47 in cancer cells." (PMID 35890254, 2022). "More recent studies have shown that CD47 mediates autophagy in RAS-expressing cancer cell lines and triggers tumour growth inhibition." (PMID 34982945, 2022). "CD47 blockades or SIRPα fusion proteins direct targeting macrophages and significantly increase both innate and adaptive immunity against many types of cancer." (PMID 36158683, 2022). "An extremely innovative approach builds on this by combining CD47-loaded red blood cell (RBC) membranes with membranes from cancer cells themselves." (PMID 36591444, 2022). "The interaction of CD47 with the SIRPα of macrophages renders cancer cells resistant to phagocytosis, thereby promoting tumor growth and metastasis." (PMID 36291839, 2022). "Research on small-molecule inhibitors targeting CD47 has also been one of the focuses for cancer immunotherapy." (PMID 36081498, 2022). "Long-standing research has provided proof that, with the activation of CD47 signaling, cancer cells will impair the immune system and evade the antitumor function of macrophages." (PMID 35464451, 2022). "CD47 has the same ability to promote cancer progression, drug resistance, poor prognosis marker and macrophage polarization as HSP." (PMID 35678681, 2022). "CD47 expression was positively associated with CD4+ T cell, CD8+ T cell, B cell, neutrophil, dendritic cell, and macrophage infiltration of numerous cancers." (PMID 35697717, 2022). "CD47 is highly expressed in cancer cells and has potential as a therapeutic target and prognostic factor in cancer patients." (PMID 36010209, 2022). "All these results confirmed that targeting the CD47/SIRPα axis can provide a new potential treatment for various cancers." (PMID 36080360, 2022). "It is of great significance to the development of therapeutic agents because of balance between their direct killing effect against cancer cells and their potentially hazardous side effects on normal CD47-positive cells." (PMID 36081498, 2022). "Anti-CD47 antibodies, which enhance cancer cell phagocytosis, can achieve higher anti-cancer efficacies when combined with chemotherapy and immunotherapy." (PMID 36059952, 2022). "Co-culture of TNF-α with cancer cells at concentrations up to 100 ng/ml resulted in a maximum fourfold increase in CD47 expression due to enhanced CD47 promotor activity." (PMID 35865547, 2022). "The gold nanoshells conjugated with anti‐CD47 antibodies efficiently killed cancer cells, and reduced the required amount and duration of NIR irradiation." (PMID 35992969, 2022). "Some pre-clinical and clinical studies have employed this checkpoint blockade concept on myeloid cells for cancer immunotherapy, including the CD47-SIRPα signaling axis, one of the hottest myeloid checkpoints in the past decade." (PMID 35646915, 2022). "These exciting experiment results make CD47 a promising new biomarker for cancer therapy and prognosis assessment." (PMID 35281519, 2022). "CD47 is a promising, emerging target for clinical cancer therapeutics but its efficacy remains a challenge." (PMID 35454837, 2022). "Then, we will discuss its potential therapeutic roles against cancer and outlines, the possible future research directions of CD47- based therapeutics against cancer." (PMID 36081498, 2022). "In preclinical studies with animal models, targeting CD47 has been shown to remarkably inhibit the growth of human cancer xenografts." (PMID 36362004, 2022).
cancer (continued). "Among many pro-tumoral functions exerted by TMAs can activate the immune response and even phagocyte cancer cells, for instance, the CD47-SIRPα interactions." (PMID 35664746, 2022). "During immunotherapy, we found that chimeric antigen receptor (CAR)-T cells that bind CD47 antigen specifically kill different types of cancer including ovarian and pancreatic cancer cells." (PMID 35678681, 2022). "Other immune checkpoints SIRPα and CD47 release a “don’t eat me” signal to prevent the recognization and phagocytosis of cancer cells by immune cells." (PMID 36300110, 2022). "Myeloid checkpoint inhibition by blockade of CD47/SIRPα interactions is a clinically advanced approach to improve antibody-based cancer immunotherapy." (PMID 36052078, 2022). "Binding of BR105 to SIRPα blocks its interaction with CD47, thereby promoting macrophage phagocytosis of cancer cells." (PMID 35256517, 2022). "This implies that dampening CD47 effectively triggers the destruction of cancer cells by the heterogeneous population of macrophages observed in vivo." (PMID 35978372, 2022). "We performed a systematic review and meta-analysis of relevant databases and conference abstracts including clinical trials using CD47 and/or SIRPα inhibitors in cancer treatment." (PMID 36439116, 2022). "We introduced the iSNAP in human THP1 monocytes (iSNAP‐MC) to rewire CD47‐SIRPα signaling and promote phagocytotic ability of the iSNAP‐MC derived iSNAP‐MΦ for cancer cell eradication." (PMID 35600645, 2022). "Recent interest in CD47 as a cancer therapeutic target has led to rapid expansion of preclinical and clinical efforts to physically block its inhibitory signaling in liquid and solid tumors that express CD47 at normal or elevated levels." (PMID 35454837, 2022). "In many studies, human cancer cells showed high CD47 expression and inhibition of the CD47-SIRPα signaling pathway using anti-CD47 antibodies promoted the removal of cancer cells." (PMID 36010209, 2022). "Recent clinical data revealed that anti-CD47 antibody induced encouraging anti-cancer effects, suggesting that CD47 is also a potential therapeutic target in ccRCC." (PMID 36291980, 2022). "Cancer cells express immune system regulators such as the cluster of differentiation (CD)-47 and PD-L1 to induce immune response resistance." (PMID 37305016, 2022). "The binding of the SPIRα on macrophages to CD47, a “don’t eat me” signal on cancer cells, protects cancer cells from being phagocytosed." (PMID 36014696, 2022). "The results showed that the nanoparticle loaded gel system induced macrophages to phagocytize cancer cells by blocking the CD47-SIRPα interaction." (PMID 35832081, 2022). "We observed that overexpression of YAP rescued the defect in the expression of IL-1β and GM-CSF cytokines and CD47 expression in SIRPγ-knockdown cancer cells, and also reversed heightened phagocytosis of the SIRPγ-knockdown cancer cells by macrophages." (PMID 35229723, 2022). "Previous reports demonstrated that CD47 activation using soluble peptides derived from thrombospondin-1(TSP-1) effectively induced cell death in several types of cancer cells." (PMID 35890254, 2022). "Responsive release of anti‐CD47 mAbs promoted polarization of M2 to M1 phenotype for enhanced cancer treatment in combination with PTX." (PMID 36257824, 2022). "Similar abscopal antitumor effects were observed in other cancer models treated with radiation and CD47 blockade." (PMID 36411318, 2022). "Cancer cells can evade macrophage-mediated phagocytosis by upregulating cell-surface expression of “don’t eat me signals”, such as CD47, PD-L1, β2M, and CD24, which bind to the phagocytosis-inhibiting receptors SIRPα, PD-1, LILRB1 and Siglec-10, respectively." (PMID 36347876, 2022). "While sparing normal cells, STI-6643 also demonstrated specific dose-response binding activity to cancer cells usually expressing higher CD47 densities at the cell surface thus promoting increased avidity." (PMID 35664753, 2022).